ENSG00000285508 (novel protein)
Synonyms: LOC128706666
Gene: Protein-coding gene on chromosome 20 (10,413,520 to 10,434,222, reverse strand). Ensembl gene ENSG00000285508.
Homologues: Orthologues: mouse Gm56450 (72% identical).